VEGFA (vascular endothelial growth factor A)
Diseases named in the same sentence as VEGFA in open-access papers (continued):
Sharing a sentence is not in itself a finding about the gene and the disease.
tumor (continued). "The VEGFA produced by these macrophages leads to transient vascular permeability, loss of vascular junctions, and increased intravasation locally at sites where tumor cells, macrophages, and blood vessels are nearby." (PMID 33339353, 2020). "An optimal predictive model for OS was obtained with the tumor subtype (triple-negative) and polymorphisms within the gene encoding the target of bevacizumab itself: VEGFA (rs833061 C/C), as well as within the genes encoding its receptors (VEGFR1; rs9582036 C/A or C/C and VEGFR2; rs1870377 T/T)." (PMID 33238394, 2020). "Moreover, the pathological situation can impact VEGF levels, as patients with more advanced tumors or several metastatic tumor sites exhibit a higher baseline level of plasma VEGFA, suggesting that VEGFA is linked to the tumor burden." (PMID 33469537, 2020). "Univariate analysis also showed a significant association between the functional genetic variant of VEGFA rs25648 with time to tumour progression, being the homozygous C and T (n = 127, 78.9%) associated with worse prognosis (HR = 1.7, 95% CI (1.1–2.6), p = 0.030)." (PMID 33353148, 2020). "Moreover, miR-497 is able to function as a tumor-suppressor miRNA in NSCLC by targeting the vascular endothelial growth factor A (VEGF-A), cyclin E1 and the Yes-associated protein 1 (YAP1)." (PMID 33266470, 2020). "It has previously been shown that radiotherapy has the ability to inhibit tumor angiogenesis and this ability might be associated with the inhibition of VEGFA expression, leading to a decreased amount of VEGFA mRNA in tissues." (PMID 32331433, 2020). "As we known, VEGFA plays a key role in tumour‐associated angiogenesis, but its role in vasculogenic mimicry remains unclear." (PMID 30945361, 2019). "Another study indicated that fluoxetine, a serotonin reuptake inhibitor, upregulated miR-572 and miR-663a consistently in NB cells and thereby inhibited their crucial targets (mir-572 - Cdkn1, Dicer1, Wnt7a; miR-663a - TGFβ1, PTEN, VEGFA) associated with NB cell differentiation and tumor evolution." (PMID 31867575, 2019). "Besides, VEGFA is predominantly produced by tumor cells, TAMs, and cancer-associated fibroblasts (CAFs)." (PMID 31892230, 2019). "Among the VEGFA AS events, patients with VEGFA/76330/ES had better survival, implying that loss of Exon8 may weaken or abolish the interaction of VEGFA with other proteins and then inhibit the growth of the tumor." (PMID 31552163, 2019). "It is well known that VEGFA is associated with tumor growth, metastasis, and angiogenesis." (PMID 31652600, 2019). "It has been reported before that the increased synthesis of MMPs in tumor cells may be associated with enhanced angiogenic ability caused by overexpression of Vascular Endothelial Growth Factor A (VEGFA), which promotes metastatic potential of cancer cells." (PMID 29337896, 2018). "Higher VEGFA expression in the tumor cells was confirmed by IHC to be associated with poorer DSF." (PMID 29587383, 2018). "DNMT3A knockdown prevented VEGFA‐driven miR‐128‐2 loss, and the increase in Bmi1 and tumor spheres." (PMID 28179359, 2017). "CRCs with VEGFA amplification or Chr6 polysomy were associated with decreased M1/M2 macrophages, reduced PD-1-expressing lymphocyte infiltration, as well as reduced stromal expression of PD-L1 at the tumor front." (PMID 28403223, 2017). "Next we investigated the association of VEGFA gene copy number status with the presence of PD-1-positive tumor infiltrating and stromal lymphocytes and PD-L1 tumoral and stromal expression at the tumor front." (PMID 28403223, 2017). "To date, targeting VEGFA has had limited success in cancer, and this may be due to anti-angiogenics causing tumor hypoxia, leading to upregulation of both VEGFA and CSC." (PMID 28504716, 2017).
tumor (continued). "In addition, ID proteins are implicated in tumor angiogenesis and induce expression of pro-angiogenic factors including hypoxia-inducible factor-1α (HIF1α), vascular endothelial growth factor A (VEGFA), interleukin-6 (IL-6)." (PMID 28881649, 2017). "However, relatively little is known about how VEGFA expression is regulated in the premalignant and early stages of tumor development when oncogenic mutations are acquired." (PMID 28415573, 2017). "VEGFA protein is encoded by the VEGFA gene, mapped at 6p21.1, a highly polymorphic region that showed association with cancer susceptibility, aggressiveness, and therapeutic response in various tumor types." (PMID 29104726, 2017). "Moreover increased VEGFA gene expression has been found frequently to be associated with tumor progression, recurrences, and the 5-year survival rate of patients that suffered from malignancy." (PMID 27777493, 2016). "Also, VEGFA can cause changes of the extracellular matrix, which plays certain roles in inflammation, wound healing, heart ischemia, atherosclerosis, tumor formation and many other pathological processes." (PMID 27588479, 2016). "Clinically, the use of anti-VEGFA antibodies in patients with neoplastic diseases could cause proteinuria." (PMID 26274923, 2015). "On the other hand, a variant Pgf (Plgf2) has been shown to inhibit tumor growth by blocking VEGFa." (PMID 24970804, 2014). "However, the precise role of TAM-derived VEGFA and its downstream mechanisms underlying the crosstalk between tumor cells and TAMs are still largely unknown." (PMID 38169627, 2024). "It has also been speculated that VEGFA amplification in some tumor types could be associated with increased micro-vessel density due to overexpression of VEGFA protein and that the density status of micro-vessels could modulate the response to anti-angiogenic therapy." (PMID 37893095, 2023). "Consequently, it is still associated with the overexpression of VEGFA in tumor tissues." (PMID 36012171, 2022). "Besides, VEGFA upregulation affects tumor progression caused by the induction of ER stress." (PMID 36727081, 2022). "In solid tumor biology, the p38 MAPK pathway has been shown to promote tumor cell survival and angiogenesis during periods of hypoxia, reoxygenation, and nutrient deficiency by inducing expression of metalloproteinases and vascular endothelial growth factor A (VEGFA)." (PMID 33920735, 2021). "Furthermore, Fuster and colleagues demonstrated that interfering with the interaction between heparan sulfate and VEGFA/FGF-2 may potentially represent a good strategy to target tumor-associated ECs, at least in lung cancer model." (PMID 32456248, 2020). "Besides inducing the transcription of the tumor suppressor p16INK4A as an endogenous feed-back loop, CDK6 also mediates the transcription of vascular endothelial growth factor A (VEGF-A), a well-characterized angiogenic factor and tumor promoter, thereby linking two hallmark cancer features." (PMID 32260549, 2020). "Therefore, our data reveal a tumor suppressor role of miR-106a-5p by targeting VEGFA, and ccRCC may be susceptible to miR-106a-5p therapy." (PMID 33224312, 2020). "Therefore, our data reveal that miR-106a-5p functions as a tumor suppressor by regulating VEGFA and ccRCC may be susceptible to miR-106a-5p therapy." (PMID 33224312, 2020). "Many cell types in the tumor microenvironment including tumor cells themselves, cancer‐associated fibroblasts, perivascular cells, and immune cells may contribute to the abnormality, for example, by secretion of cytokines including but not limited to VEGFA." (PMID 31318171, 2019). "Therefore, we hypothesized that Bclaf1 is able to induce VEGFA expression to promote tumor-associated angiogenesis and consequently tumor growth." (PMID 30367150, 2019).
tumor (continued). "As the cancer cells in our xenografts express VEGFA and xenograft vascularisation is sensitive to inhibition of VEGFR signalling, this led us to hypothesise that the xenograft-associated macrophages can potentiate tumour angiogenesis that is driven by xenograft-supplied VEGFA." (PMID 30396905, 2018). "However, the loss of VEGFA in tumor-infiltrating myeloid cells (the majority of which are TAMs) failed to inhibit the progression of subcutaneous and autochthonous (MMTV-PyMT) tumors, although it increased the susceptibility of tumors to chemotherapeutic cytotoxicity." (PMID 24314323, 2013). "Moreover, previous findings in an experimental SCC model, demonstrating that elevated VEGFA levels were associated with increased tumor cell invasion and angiogenesis, indicate an indirect mechanism by which miR-361-5p might promote SCC progression." (PMID 23166713, 2012). "The VEGFA–VEGFR2 signaling axis is a central driver of tumor angiogenesis and a major clinical target of anti-angiogenic therapies." (PMID 41516402, 2026). "Pathway analysis revealed activation of inflammatory and tumor microenvironment pathways, and upstream regulator analysis identified VEGFA and CCL2 as potential drivers." (PMID 41977309, 2026). "Nevertheless, our findings reveal that high VMP1 expression predicts poor survival in GBM and drives pro‐angiogenic tumor growth independently of autophagy via VEGFA‐VEGFR2 signaling." (PMID 41589276, 2026). "In this study, we reveal SHP2 as a binding partner of pY1175 and show that SHP2 cooperates with PLCγ to mediate VEGFA-induced permeability in both healthy and tumor vasculatures." (PMID 41716992, 2026). "Despite elevated levels of SerRS protein in RCC tumor tissues, SerRS repressive regulatory function on VEGFA was impaired." (PMID 42104647, 2026). "When tumor-derived angiogenic mediators like VEGFA, ANGPT2, and HIF-regulated cytokines are disseminated, they promote the formation of new blood vessels and alter the local stroma, making it easier for metastases to grow." (PMID 41596524, 2026). "In vivo, EVs accelerated tumor growth and activated prosurvival (p-AKT, BCL-2), angiogenic (VEGFA, CD31), and epithelial-mesenchymal transition-associated (vimentin) pathways." (PMID 41828681, 2026). "TNF+ MCs recruit immune cells through pro-inflammatory actions, while VEGFA+ MCs support tumor growth and suppress immune responses." (PMID 40932351, 2026). "In the cohort missing VEGFA, tumours developed faster and all animals presented tumours within five weeks." (PMID 40721510, 2026). "Biodistribution and proteomic analyses confirmed efficient BBB penetration, tumor-selective accumulation, and suppression of VEGFA/C, MMP-9, PDGFB, and SERPINE1." (PMID 41993637, 2026). "By targeting VEGFA, miR-16-5p contributes to the inhibition of neovascularization, thereby limiting nutrient supply to the tumor and curbing its growth potential." (PMID 41561226, 2026). "According to a previous pan-cancer single-cell transcriptomic atlas of tumor-infiltrating myeloid cells, the proportion of TNF+ MCs and VEGFA+ MCs was significantly associated with cancer prognosis." (PMID 40932351, 2026). "Our findings were further reinforced by using therapeutics that target VEGFA in a VMP1‐driven tumor model." (PMID 41589276, 2026). "Consistent with earlier studies showing propofol can disrupt tumor angiogenesis, we observed that propofol treatment significantly reduced VEGFA expression and impaired VEGFR2 activation in ECs." (PMID 41524974, 2026). "In OC, LINC01123 regulates VEGFA through hsa-miR-516b-5p, impacting angiogenesis and tumor progression." (PMID 40255398, 2025). "In CK19+ HCC, TAM subpopulations with M2‐like features (SPP1+ TAMs) are enriched and promote tumour migration by activating VEGFA signalling." (PMID 40665579, 2025).
tumor (continued). "A hypoxic microenvironment beneath “leading edge” cells defines module 2, marked by expression of angiogenesis-related genes (e.g. Vegfa; vascular endothelial growth factor A) and a sharp boundary between tumor endothelial cells and ARG1hi macrophages." (PMID 40705858, 2025). "Immunohistochemical analyses of A549-Par and A549PM xenograft tumor tissues revealed significant overexpression of VEGFA and vascular markers such as CD31 and CD133 in A549-PM-derived tumors." (PMID 40940965, 2025). "This subpopulation of myeloid cells promotes neovascularization in tumor tissue by the expression of mediators such as vascular endothelial growth factor A (VEGF-A) or transforming growth factor beta (TGF-β)." (PMID 41440002, 2025). "CEMIP enhances angiogenesis and vasculogenic mimicry by increasing VEGFA secretion, thereby facilitating tumor dissemination." (PMID 41152975, 2025). "Intriguingly, ATF4 directly binds the VEGFA promoter to enhance transcription during ER stress, a pathway co-opted in tumor angiogenesis." (PMID 41010531, 2025). "First, PTX-resistant cells have been shown to exhibit an overexpression of pro-angiogenic factors, including Vascular Endothelial Growth Factor A (VEGFA), which promotes tumor growth and metastasis." (PMID 40282535, 2025). "In vivo experiments using nude mice demonstrated that APOC1 knockdown significantly reduced the expression of endothelial differentiation markers CD31 and VEGFA in tumor tissues." (PMID 39873475, 2025). "VEGFA is a key angiogenic factor in tumors, playing a significant role in the initial stages of tumor development, progression, and metastasis." (PMID 40474298, 2025). "NRP-1 is a cell surface receptor that plays a multisystem role in angiogenesis, tumor progression, and axonal guidance by acting as a receptor for ligands such as vascular endothelial growth factor-A, integrins, and transforming growth factor-β." (PMID 40584180, 2025). "VEGFA overexpression is also detected in lymph node metastases of EAC, with some studies demonstrating VEGFA mutation being identified in 30–60% of metastasized EAC cases, suggesting its involvement in tumor metastasis." (PMID 41369383, 2025). "By neutralizing VEGF and preventing the activation of VEGF tyrosine kinase receptors VEGFR1 and VEGFR2 on endothelial cells, it attenuates VEGFA-dependent tumor blood vessel formation, promotes tumor vascular normalization and promotes tumor cell apoptosis." (PMID 39995836, 2025). "Our findings highlight a novel mechanism by which S1P promotes angiogenesis, not only by directly enhancing VEGFA expression in tumor cells but also through its effects on macrophages." (PMID 40589755, 2025). "BVZ downregulates angiogenesis by binding to circulating vascular endothelial growth factor A, altering its interaction with endothelial receptors, thus reducing tumor blood supply." (PMID 40598793, 2025). "Further, Treg cells are recruited in response to tumor hypoxia and are producers of VEGFA to promote angiogenesis and further support an immunosuppressive TME." (PMID 39567756, 2025). "One of the most important factors is VEGFA, which is upregulated in most tumours and plays an indispensable role in their stroma." (PMID 41009413, 2025). "USP13 also inhibited tumor angiogenesis through downregulating VEGFA, and recombinant VEGFA blocked the inhibition of the conditioned medium from USP13-overexpressing CRC cells against HUVEC angiogenesis in vivo." (PMID 40746889, 2025). "TAMs form TMEM doorways with tumour cells and endothelial cells, stimulating VEGFA secretion, which disrupts endothelial junctions and increases vascular permeability." (PMID 40361472, 2025). "HCC growth often requires angiogenesis which is regulated by factors like VEGFA, which promotes blood supply to the tumour and facilitate its growth and metastasis." (PMID 40263693, 2025).
tumor (continued). "This resulted in effective genome editing of VEGFA within tumor cells, a reduction in VEGFA expression, suppression of lung metastasis and orthotopic OS severity, as well as a decline in angiogenesis and bone lesions, all without any noticeable toxicity." (PMID 40391083, 2025). "This study systematically characterized CRC tumor cell heterogeneity through single-cell RNA sequencing, leading to the first identification of the VEGFA+TC subpopulation with EMT activation and high metastatic potential." (PMID 40574852, 2025). "When compared the top 20% of VEGFA expressing tumor samples to the bottom 20% expressing tumors and found that POLH goes up 1.69-fold (FDR 1 × 10−10), POLI goes up 2.06-fold (FDR 1.3 × 10−15) and REV3L goes up 1.62-fold (FDR 3.8 × 10−6)." (PMID 39468223, 2025). "VEGFA is crucial for enhancing tumor angiogenesis, promoting migration and invasion, and contributing to the formation of an immunosuppressive tumor microenvironment." (PMID 40474298, 2025). "M2 macrophages express factors like arginase-1 and VEGFA, promoting angiogenesis, immunosuppression, and metastasis, while reducing the proportion of anti-tumor M1 macrophages." (PMID 40672391, 2025). "Mechanistically, collagen promoted VEGFA expression in tumor cells and directly facilitated vessel formation and the proliferation of HUVEC endothelial cells by upregulating SOX18 expression and its transcriptional activity." (PMID 39823457, 2025). "Neutrophils contribute to the establishment of pre-metastatic niches by secreting chemokines such as ARG1, CXCL1, CXCL2, CXCL10, CCL2, CXCR2, and vascular endothelial growth factor A (VEGFA), which attract tumor cells to metastatic sites." (PMID 40227814, 2025). "Compared with the growth of D5 tumor implants in the control mice, the growth of D5 tumor implants in the cured mice treated with an anti-VEGFA activity (G6.31.2a alone, G6.31.2a plus 4D5.2a, or TG-VHS) was remarkably slower." (PMID 40906526, 2025). "Vascular endothelial growth factor receptor 2 (VEGFR2) is one of the main targets for anti-angiogenic tumor therapy, as its activation with VEGFA induces proliferation, migration, and angiogenesis in solid tumors." (PMID 40841907, 2025). "VEGFA facilitates macrophage polarization toward the M2 phenotype within the tumor microenvironment." (PMID 40129528, 2025). "Specifically, when cultured under normoxic conditions, HIF-1α expression in TAMs is stabilized by tumor-derived lactate, leading to the transcription of the VEGFA gene." (PMID 40760493, 2025). "TRPM7 enhances the expression of angiogenesis factors, such as VEGFA, by activating specific pathways, thereby promoting tumor angiogenesis." (PMID 40740874, 2025). "Mechanistically, collagen fosters angiogenesis by directly activating endothelial cells and increasing the expression and secretion of VEGFA in tumor cells." (PMID 39823457, 2025). "VEGFA is in mediating tumor angiogenesis, with its expression being controlled by oncogenes, diverse growth factors, and hypoxia." (PMID 40989165, 2025). "Excessive lactate production can also induce TAMs to produce VEGFA, which further activates the formation of tumor lymphatic vessels and blood vessels." (PMID 40034817, 2025). "Here, we identified VEGFA‐expressing tumor cells in ABCP responders, which is consistent with previous LUAD studies." (PMID 40843133, 2025). "This process promotes VEGFA release, drives angiogenesis, and suppresses T cell-mediated anti-tumor responses." (PMID 41028519, 2025). "VEGFA, a well-characterized pro-angiogenic driver, is known to promote tumor vascularization and immune evasion." (PMID 40943183, 2025). "Concurrently, TGF-β upregulates vascular endothelial growth factor A expression, establishing a positive feedback loop that fosters tumor angiogenesis and reinforces an immunosuppressive microenvironment." (PMID 41445735, 2025).